TSPAN15 (tetraspanin 15)
Description:
Part of TspanC8 subgroup, composed of 6 members that interact with the transmembrane metalloprotease ADAM10. This interaction is required for ADAM10 exit from the endoplasmic reticulum and for enzymatic maturation and trafficking to the cell surface as well as substrate specificity. Different TspanC8/ADAM10 complexes have distinct substrates. Promotes ADAM10-mediated cleavage of CDH2. Negatively regulates ligand-induced Notch activity probably by regulating ADAM10 activity.
Synonyms: NET7; TM4SF15; NET-7; 2700063A19Rik
Tractability: Small molecule: a structure with a bound ligand is known. Antibody: UniProt places it where antibodies can reach, with high confidence; its Gene Ontology location is reachable by antibodies, with high confidence; UniProt predicts a signal peptide or a membrane-spanning region.
Gene: Protein-coding gene on chromosome 10 (69,451,150 to 69,507,676, forward strand). Ensembl gene ENSG00000099282.
Subcellular location: Cell membrane; Late endosome membrane
Subcellular location (Human Protein Atlas): Nuclear bodies; Plasma membrane; Cytosol; Vesicles
Pathways (Reactome):
Metabolism of proteins: Amyloid fiber formation
Gene Ontology:
Molecular function: enzyme binding; protein binding
Biological process: negative regulation of Notch signaling pathway; protein localization to plasma membrane; protein maturation; regulation of membrane protein ectodomain proteolysis; regulation of Notch signaling pathway
Cellular component: late endosome membrane; plasma membrane; endoplasmic reticulum lumen; cell surface; membrane; tetraspanin-enriched microdomain
Genetic constraint (gnomAD): Loss-of-function variants: 17 observed, 28.16 expected, observed/expected ratio (o/e) 0.6, 90% interval 0.41 to 0.91. The upper end of that interval is the gene's LOEUF score, 0.91, which puts it in group 3 of 6, group 1 being the genes least tolerant of losing a copy. Missense variants: 282 observed, 336.98 expected, observed/expected ratio (o/e) 0.84, 90% interval 0.76 to 0.92. Synonymous variants: 146 observed, 136.88 expected, observed/expected ratio (o/e) 1.07, 90% interval 0.93 to 1.22.
Homologues: Orthologues: chimpanzee TSPAN15 (100% identical), macaque TSPAN15 (98% identical), rabbit TSPAN15 (93% identical), pig TSPAN15 (93% identical), mouse Tspan15 (92% identical), guinea pig TSPAN15 (91% identical), rat Tspan15 (91% identical), dog TSPAN15 (84% identical), tropical clawed frog tspan15 (70% identical), zebrafish tspan15 (65% identical). Paralogues in human: TSPAN33 (28% identical), TSPAN17 (26% identical), TSPAN5 (24% identical), TSPAN14 (22% identical), TSPAN11 (21% identical), TSPAN9 (20% identical), TSPAN10 (20% identical), TSPAN3 (19% identical), CD151 (19% identical), TSPAN4 (19% identical), TSPAN1 (18% identical), TSPAN6 (18% identical), and 20 more.
Diseases named in the same sentence as TSPAN15 in open-access papers:
TSPAN15 is named in the same sentence as 32 diseases in open-access papers, as found by Europe PMC text mining. Sharing a sentence is not in itself a finding about the gene and the disease. The quoted sentences say what the papers report.
esophageal squamous cell carcinoma (5 papers, 2020 to 2024). Esophageal squamous cell carcinoma (ESCC) is a type of esophageal carcinoma (EC) that can affect any part of the esophagus, but is usually located in the upper or middle third. "High TSPAN15 expression in esophageal squamous cell carcinoma tissues is significantly associated with lymph node and distant metastasis, and poor prognosis." (PMID 36941633, 2023). "One study reported that the expression of Tspan15 (mRNA and protein) was increased in squamous cell carcinomas of the esophagus (OSCC) and in OSCC-derived cell lines." (PMID 38667323, 2024). "The upregulation of Tetraspanin 15 (TSPAN15) has been reported in esophageal squamous cell carcinoma (OSCC) tissues." (PMID 37686524, 2023). "BTRC can interact with TSPAN15 and promotes esophageal squamous cell carcinoma metastasis by activating NF-kB signaling." (PMID 36199080, 2022). "TSPAN15 could augment metastatic capabilities but not proliferation of esophageal squamous cell carcinoma cells." (PMID 36941633, 2023).
breast carcinoma (3 papers, 2019 to 2025). "In our results, the expression levels of TSPAN1, TSPAN13, and TSPAN15 in breast cancer were all increased." (PMID 31182966, 2019). "Our TSPAN1 results are consistent with those previously reported, so we speculate that TSPAN13 and TSPAN15 may be potential cancer-related genes for breast cancer." (PMID 31182966, 2019). "Other genes we replicated have been reported to play a role in breast cancer progression such as HOXD9, TDRD10, SH3PXD2A and TSPAN15, although these studies did not involve DNA methylation data as a prognostic marker." (PMID 39825380, 2025). "Analyses of the expression levels of all 33 tetraspanins revealed significantly higher expression of TSPAN1, TSPAN15, TSPAN8, TSPAN11, TSPAN29, and TSPAN27 in the breast cancer spheres than in non-CSCs." (PMID 31253779, 2019).
hepatocellular carcinoma (3 papers, 2020 to 2024). A malignant tumor that arises from hepatocytes. "Furthermore, positive immunodetection of Tspan15 in hepatocellular carcinoma was correlated to cancer recurrence, and its overexpression in hepatoma cell line HepG2 increased cell proliferation through CTGF (connective tissue growth factor) production and ERK1/2 phosphorylation." (PMID 38667323, 2024). "TSPAN15, the common target for both aptamers selected for OvCar-3 cells, is a transmembrane protein that is related to esophageal carcinoma, oral carcinoma, liver hepatocellular carcinoma (LIHC), and hepatocellular carcinoma (HCC)." (PMID 37047289, 2023).
esophageal cancer (2 papers, 2021 to 2023). A primary or metastatic malignant neoplasm involving the esophagus. "Targeting Tspan15 also has potential as an anti-cancer strategy, given its pro-invasive role and capacity to promote esophageal cancer growth in a mouse model." (PMID 34201472, 2021). "A scissor-independent role for Tspan15 was recently reported to explain Tspan15′s role in promoting esophageal cancer cell invasion." (PMID 34201472, 2021).
metastatic tumor (2 papers, 2023 to 2024). "Significant gene upregulation of these tetraspanins (CD53, ROM1, TSPAN3, TSPAN12, TSPAN15, and UPK1B) within immune cells in metastatic tumor suggests their potential involvement in the influence of immune responses." (PMID 38255741, 2024). "The three potential targets FXYD3, ALPP, and TSPAN15 were further explored regarding their expression profile in non-tumoral (normal), primary site tumor, and metastatic tumor tissues, using GeneChip data from TNMplot database." (PMID 37047289, 2023).
Arterial thrombosis (1 paper, 2022). The formation of a blood clot inside an artery. "Theoretically, a therapeutic strategy designed to activate Tspan15/ADAM10 or Tspan33/ADAM10 may provide a novel treatment for arterial thrombosis, since irreversible shedding of GPVI would render platelets non-responsive to collagen." (PMID 35269584, 2022).
Arthritis (1 paper, 2022). Inflammation of a joint. "During TNF-mediated arthritis, the S4a(Prg4high/Tspan15+) LSFs preserve some of their homeostatic marker gene identity, but also show an expansion in the diversity of their transcriptome, indicating that their reparative functions might be affected after disease onset." (PMID 35879783, 2022).
bladder cancer (1 paper, 2024). "Taken together, these data indicated, for the first time in T24 bladder cancer cells, that Tspan15 was implicated in the ectodomain cleavage of N-cadherin by ADAM10 since blocking Tspan15 alone reduced the NTF amount released in the extracellular compartment." (PMID 38667323, 2024). "Our data demonstrated, for the first time in T24 invasive bladder cancer cells, the requirement of Tspan15 in ADAM10-mediated shedding of N-cadherin ectodomain." (PMID 38667323, 2024). "We first demonstrated, in invasive T24 bladder cancer cells, that N-cadherin was cleaved by ADAM10 generating NTF in the extracellular environment and leaving a membrane-anchored CTF1 fragment and that Tspan15 is required for ADAM10 to induce the selective N-cadherin cleavage." (PMID 38667323, 2024). "By targeting Tspan15 to block ADAM10 activity on N-cadherin, GW501516 could prevent NTF pro-tumoral effects and be a promising molecule to treat bladder cancer." (PMID 38667323, 2024). "To date, no data are available on the expression of Tspan15 in relation to the grade and stage of bladder cancer." (PMID 38667323, 2024).
ischemic stroke (1 paper, 2022). A stroke disorder caused by obstruction of blood flow to the brain, due to thrombotic (local blood clot formation) or embolic (due to a blood clot or other material traveling from another site) event. "In conclusion, a major finding of this study is the identification of Tspan15/ADAM10 and Tspan33/ADAM10 as molecular scissors for GPVI, a clinically relevant antiplatelet target for myocardial infarction and ischemic stroke." (PMID 35269584, 2022).
lymph node metastasis (1 paper, 2018). "High expression of TSPAN15 was significantly associated with lymph node metastasis (P < 0.001), distant metastasis (P = 0.003), and advanced clinical stage (P = 0.001)." (PMID 29650964, 2018).
neuroblastoma (1 paper, 2023). Neuroblastoma (NB) is the most common solid, extracranial childhood tumor. "In order to visualize donor cell‐derived Tspan15‐GFP‐positive EVs contacting the plasma membrane of target cells, we performed live cell imaging in neuroblastoma‐derived N2a cells using time‐lapse video microscopy." (PMID 38938373, 2023). "Since available Tspan15‐specific antibodies do not work for immunostaining, we expressed Tspan15‐GFP fusion protein in N2a cells derived from neuroblastoma." (PMID 38938373, 2023).
osteosarcoma (1 paper, 2024). A usually aggressive malignant bone-forming mesenchymal neoplasm, predominantly affecting adolescents and young adults. "Also, Tspan15 was found to be negatively regulated by miR-16-5p, and downregulated Tspan15 significantly decreased the metastasis and growth of osteosarcoma MG63 cells via inhibiting the PI3K/Akt pathway." (PMID 38389703, 2024).
ovarian carcinoma (1 paper, 2023). A malignant neoplasm originating from the surface ovarian epithelium. "Thus, FXYD3 and ALPP could be used as biomarkers for primary sites of ovarian tumors and TSPAN15 as a biomarker for ovarian cancer metastasis." (PMID 37047289, 2023).
pneumococcal pneumonia (1 paper, 2018). A febrile disease caused by STREPTOCOCCUS PNEUMONIAE. "Association tests pointed to single nucleotide polymorphism (SNP) rs201967957 (gene MEIS1; chromosome 2; p-valueIBS = 3.71 × 10−13) and rs576099063 (gene TSPAN15; chromosome 10; p-valueIBS = 2.36 × 10−8) as the best candidate variants associated to pneumococcal pneumonia." (PMID 29751582, 2018).
pneumonia (1 paper, 2018). An acute, acute and chronic, or chronic inflammation focally or diffusely affecting the lung parenchyma, caused by an infection in one or both of the lungs (by bacteria, viruses, fungi, or mycoplasma.). "By analyzing various transcriptomic data repositories, we found strong supportive evidence for the role of MEIS1, TSPAN15 and APOBR (encoding the receptor of the APOB protein) in pneumonia in mouse and human models." (PMID 29751582, 2018).
pulmonary embolism (1 paper, 2021). The obstruction of the pulmonary artery or one of its branches by an embolus, sometimes associated with infarction of the lung. "TSPAN15 is correlated with a few different diseases involving thrombosis—venous thromboembolism, pulmonary embolism, and stroke in three independent GWAS studies conducted among European or African American populations." (PMID 33860000, 2021).
venous thromboembolism (1 paper, 2021). Occlusion of the lumen of a vein by a thrombus that has migrated from a distal site via the blood stream. "Some of the variants located in introns meet the criteria: for instance, an association between an SNP within TSPAN15 (rs78707713) and venous thromboembolism has a p value of 2 × 10−16." (PMID 33860000, 2021).
tumor (11 papers, 2015 to 2025). "Interestingly, for all tumor types, TSPAN15 is described as especially associated with metastasis, indicating that cells overexpressing this protein have increased proliferative, migratory, and invasive capabilities." (PMID 37047289, 2023). "ALPP expression was higher in primary site tumor samples when compared to normal and metastatic samples while TSPAN15 was upregulated in primary site tumor and metastatic samples as compared to normal samples." (PMID 37047289, 2023). "Tspan15 is upregulated in several cancers and was recently shown to promote cancer cell invasion in vitro and tumor cell formation in vivo, and N-cadherin shedding was shown to be impaired following Tspan15 knockdown in oral squamous carcinoma cell lines." (PMID 34201472, 2021). "TSPAN15 is believed to enhance tumor stemness, and it has the ability to promote tumor growth and recurrence." (PMID 32694936, 2020). "Multivariate Cox proportional regression analysis further revealed that tumor location (P < 0.001), differentiation (P = 0.001), and TSPAN15 expression (P = 0.007) are independent prognostic factors for the overall survival of OSCC patients." (PMID 29650964, 2018). "Functional studies in vitro and in vivo revealed that TSPAN15 promoted cell migration, cell invasion, and tumor metastasis." (PMID 29650964, 2018). "In this study, we demonstrate that TSPAN15 is upregulated in OSCC samples compared with their matched non-tumor counterparts." (PMID 29650964, 2018). "The tumorigenic ability of TSPAN15 was assessed by XTT cell growth assay, foci formation assay, soft agar assay and xenograft tumor mouse model." (PMID 29650964, 2018). "Some tetraspanins, such as TSPAN15, can enhance tumor cell proliferation ability, while other family members, such as CD9, CD63, TSPAN1, TSPAN7, and TSPAN31, can antagonize apoptosis and facilitate tumor cell survival." (PMID 34540692, 2021). "Our previous RNA-seq analysis revealed that TSPAN15 was overexpressed in three tested OSCC tumor tissues compared to their corresponding non-tumor tissues." (PMID 29650964, 2018). "Overexpression of TSPAN15 was detected in 169/266 (63.5%) of informative OSCC tumor tissues compared with the corresponding non-tumor tissues." (PMID 29650964, 2018).
cancer (9 papers, 2018 to 2025). A tumor composed of atypical neoplastic, often pleomorphic cells that invade other tissues. "TSPAN15, also known as tetraspanin-15, is part of a family of genes implicated in cell adhesion and migration and associated with cancer progression in several cancer cell lines." (PMID 41409683, 2025). "In some specific types of HCC, the level of TSPAN15 is upregulated, which positively associates with the stemness of cancer cells and recurrence of cancer significantly." (PMID 34540692, 2021). "Conversely, mounting evidence denotes that TSPAN15 serves as an oncogene, exerting an important influence on pathogenesis, progression, metastasis, and resistance to chemotherapy in cancer." (PMID 41347075, 2025). "The therapeutic modulation of Tspan15 expression is an attractive approach to treating cancer since Tspan15 is overexpressed in several cancers." (PMID 38667323, 2024). "The function of the Tspan15/ADAM10 scissor has started to be investigated using mouse models and cancer cell lines deficient in or over-expressing Tspan15." (PMID 34201472, 2021). "There are few studies on TSPAN15, and its effect on cancer was reported less frequently." (PMID 31182966, 2019). "Altogether, TSPAN1, TSPAN15, TSPAN29, and CD151 could support cancer cell growth, while TSPAN31, TSPAN6, CD9, CD37 could inhibit cancer growth." (PMID 36941633, 2023). "It will be important to understand Tspan15′s ADAM10-dependent role, for example via shedding of N-cadherin or novel substrates, and ADAM10-independent role, via NF-κB signaling, in different cancers to realize optimal targeting strategies." (PMID 34201472, 2021).
digestive system cancer (1 paper, 2024). A primary or metastatic malignant neoplasm involving any part of the digestive system. "Generally, the expression of CD9, CD151, Tspan1, Tspan5, Tspan8, Tspan12, Tspan15, and Tspan31 are upregulated, facilitating the migration and invasion of digestive system cancer cells." (PMID 38389703, 2024).
TSPAN15 also shares sentences with these, for which no sentence is quoted: anxiety disorder (1 paper); autism (1); chronic thromboembolic pulmonary hypertension (1); Creutzfeldt Jakob disease (1); idiopathic pulmonary arterial hypertension (1); metabolic disease (1); myocardial infarction (1); oral carcinoma (1); ovarian tumors (1); pancreatic adenocarcinoma (1); prostate carcinoma (1); Stroke (1).